SURF2 (surfeit 2)
Synonyms: Surf-2
Tractability: Antibody: its Gene Ontology location is reachable by antibodies, with high confidence. PROTAC: ubiquitination databases record sites on it.
Gene: Protein-coding gene on chromosome 9 (133,356,545 to 133,362,215, forward strand). Ensembl gene ENSG00000148291.
Subcellular location (Human Protein Atlas): Nucleoli; Nucleoli rim; Nucleoplasm
Gene Ontology:
Molecular function: protein binding
Genetic constraint (gnomAD): Loss-of-function variants: 35 observed, 26.24 expected, observed/expected ratio (o/e) 1.33, 90% interval 1.02 to 1.75. The synonymous counts are far from expectation, so gnomAD's model fits this gene poorly and the ratio says little. Missense variants: 415 observed, 324.9 expected, observed/expected ratio (o/e) 1.28, 90% interval 1.18 to 1.38. Synonymous variants: 173 observed, 123.79 expected, observed/expected ratio (o/e) 1.4, 90% interval 1.23 to 1.59.
Homologues: Orthologues: chimpanzee SURF2 (99% identical), macaque SURF2 (95% identical), pig SURF2 (75% identical), dog SURF2 (75% identical), mouse Surf2 (70% identical), rat Surf2 (70% identical), guinea pig SURF2 (67% identical), tropical clawed frog surf2 (53% identical).